RPS20 (ribosomal protein S20)
Diseases named in the same sentence as RPS20 in open-access papers:
RPS20 is named in the same sentence as 49 diseases in open-access papers, as found by Europe PMC text mining. Sharing a sentence is not in itself a finding about the gene and the disease. The quoted sentences say what the papers report.
colorectal cancer (12 papers, 2017 to 2024). A primary or metastatic malignant neoplasm that affects the colon or rectum. "Analysis of the genomic information from several families with a hereditary predisposition to non-polyposis colorectal cancer (CRC) revealed various mutations in the coding region of the RPS20 gene encoding the uS10 ribosomal protein." (PMID 38290548, 2024). "To this end, we knocked down RPS3, RPS6 and RPS20 as well as RPL7 in human HCT116 colorectal cancer cells that are either WT or deficient for p5343." (PMID 39609413, 2024). "Among these genes is RPS20, which encodes the ribosomal protein uS10 (previously named as S20), mutations of which are associated with colorectal cancer." (PMID 35682850, 2022). "In recent years, mutations in ribosomal protein genes have been found in different types of cancer, such as ribosomal protein S20 (RPS20) gene mutations in colorectal cancer." (PMID 33854615, 2021). "Additionally, identification of a likely disease-predisposing variant in RPS20 expands the phenotypic spectrum of RPS20-related cancers and emphasize that this gene is relevant to include in colorectal cancer gene panels." (PMID 33193653, 2020). "Moreover, the recent advances in molecular techniques, in particular Next-Generation Sequencing, have led to the identification of many new genes involved in the predisposition to colorectal cancers, such as RPS20, POLE, POLD1, AXIN2, NTHL1, MSH3, RNF43 and GREM1." (PMID 36768460, 2023). "Different from genes that contribute to all six cancer subtypes, RPS20 has only been identified in limited cancer subtypes, including colorectal cancer and glioblastoma." (PMID 29152097, 2017). "In addition, mutations in the ribosomal protein genes have been found to be involved in cancers such as endometrial cancer (RPL22), chronic lymphoblastic leukemia (RPS15), colorectal cancer (RPS20), and glioma (RPL5)." (PMID 34827869, 2021). "Mutation of Ribosomal Protein S20 (RPS20) in the germline cells might cause hereditary nonpolyposis colorectal carcinoma." (PMID 33435549, 2021). "A number of mutations in the RPS20 gene encoding the ribosomal protein uS10 have been found to be associated with a predisposition to hereditary non-polyposis colorectal carcinoma (CRC)." (PMID 35682850, 2022). "The first evidence of the association of mutations in the RPS20 gene with human diseases has been reported in the study, from which it becomes clear that they are related to a predisposition to hereditary non-polyposis colorectal carcinoma (CRC)." (PMID 35682850, 2022).
glioblastoma (8 papers, 2015 to 2025). The most malignant astrocytic tumor (WHO grade IV). "In the central nervous system, RPS20 serves as a prognostic marker in glioblastoma and medulloblastoma while also acting as a biomarker and potential therapeutic target in Alzheimer’s disease and autoimmune hepatitis." (PMID 40710323, 2025). "RPS11 and RPS20 have been proposed as prognostic markers in glioblastoma and the down-regulation of RPL10 correlates with altered treatment response to dimethylaminoparthenolide (DMAPT) in pancreatic cancer." (PMID 29530001, 2018). "Moreover, increased expression of ribosomal proteins RPS11 and RPS20 predicts shorter survival in glioblastoma patients." (PMID 35281852, 2022). "In glioblastoma, increased expression of uS17/RPS11 and uS10/RPS20 enhanced stress-resistant CSC phenotypes." (PMID 34627375, 2021).
viral infection (6 papers, 2018 to 2025). "Supporting a functional role of RQC in vaccinia viral infection, viral replication was impaired in cells deficient in ZNF598 activity or expressing a ubiquitination-deficient version of Rps20." (PMID 36187485, 2022). "It is likely that the upregulation of RPS20 in viral infection provides a mechanism for stimulation of hematopoietic stem cells and red blood cell development for increased production of immune cells like neutrophils for recruitment to the site of infection." (PMID 33240937, 2020).
medulloblastoma (5 papers, 2006 to 2025). A malignant, invasive embryonal neoplasm arising from the cerebellum. "RPS20 has been suggested as a candidate gene associated with medulloblastoma, the most common malignant brain tumor in children." (PMID 36011399, 2022). "Nonetheless, our results suggest that better appreciation of the relative contributions of EEF1D, RPL30, RPS20, and their associated regulatory mechanisms will impact our understanding of medulloblastoma biology." (PMID 16968546, 2006). "We demonstrate that gain of 8q and expression levels of three 8q-mapped candidate genes (EEF1D, RPL30, RPS20) are associated with adverse outcome in medulloblastoma." (PMID 16968546, 2006). "Alternatively, we assayed the expression of EEF1D, RPL30, and RPS20 with qRT-RTPCR in twelve available medulloblastoma specimens, including those analyzed by Affymetrix U133 Plus 2.0 microarrays." (PMID 16968546, 2006).
colon carcinoma (3 papers, 2018 to 2024). "This suggests that RPS15, like RPS20, may contribute to the development of liver metastasis in colon cancer by promoting cell proliferation." (PMID 38838053, 2024).
familial colorectal cancer type X (3 papers, 2020 to 2024). Hereditary nonpolyposis colorectal cancer characterized by the absence of germline mutations in DNA mismatch-repair genes. "Another study demonstrated that a germline mutation in RPS20, encoding a component of the small ribosomal subunit, increases the predisposition to develop a particular form of hereditary CRC named familial colorectal cancer type X (FCCX)." (PMID 34439343, 2021). "The mutation in RPS20 has been associated with a subtype of hereditary colorectal cancer (CRC) called Familial colorectal cancer type X (FCCTX), in which no mutation in mismatch repair genes was reported, but several pathogenic variants of predisposing genes were observed." (PMID 33076379, 2020).
Alzheimer disease (2 papers, 2024 to 2025). A progressive, neurodegenerative disease characterized by loss of function and death of nerve cells in several areas of the brain leading to loss of cognitive function such as memory and language. "Notably, six of these proteins (RPS3A, RPS4X, RPS8, RPS14, RPS20 and RPL31) were upregulated in brain capillaries of Alzheimer’s disease patients." (PMID 38732249, 2024).
anemia (2 papers, 2013 to 2017). A reduction in the number of red blood cells, the amount of hemoglobin, and/or the volume of packed red blood cells. "Heterozygous missense mutations of Rps20 show a mild macrocytic anemia reflecting the fact that mutations causes a hypomorphic allele rather than true happloinsufficiency." (PMID 27870251, 2017).
autoimmune hepatitis (2 papers, 2012 to 2025). Hepatitis caused by autoantibodies. "They then produced an autoimmune hepatitis-specific protein chip, and found three new antigens, ribosomal protein S20 (RPS20), Alba-like, and dUTPase, that could be used as highly specific biomarkers for autoimmune hepatitis, and validated this with ELISA." (PMID 22214245, 2012).
Diamond-Blackfan anaemia (2 papers, 2022 to 2024). "Also, for the Blanco Orejinegro and Limonero, RPS27 and RPS20 are located in CSS cluster regions on BTA3 and BTA14, respectively, and mutations in these genes can cause Diamond-Blackfan anaemia." (PMID 38571912, 2024).
hereditary non-polyposis colorectal carcinoma (2 papers, 2022 to 2025). "Furthermore, germline mutations in RPS20 cause predisposition to hereditary nonpolyposis colorectal carcinoma." (PMID 40710323, 2025).
lung carcinoma (2 papers, 2013 to 2019). "RPL37, RPS15, and RPS20 were cloned into a mammalian expression vector and transfected into H1299 lung carcinoma cells alongside Mdm2." (PMID 23874713, 2013).
ovarian carcinoma (2 papers, 2022 to 2024). A malignant neoplasm originating from the surface ovarian epithelium. "A seven-hub-molecule-signature model (RRAS2, HIST1H2BK, ALB, RPL23A, HIBCH, RPS20, and EIF3E) from those 1198 mtDEPs is established to predict the survival time of ovarian cancer." (PMID 35498135, 2022). "A seven-hub-molecule-signature model (HIBCH, HIST1H2BK, ALB, EIF3E, RPS20, RRAS2, and RPL23A) from a multivariate regression analysis can predict the survival risks of ovarian cancer." (PMID 35498135, 2022).
breast carcinoma (1 paper, 2017). "We identify RPSA, RPS5, RPS20, RPL5, RPL11 and RPL23A as six interesting cancer driver candidates and show a tumor suppressor role for RPL5 in the context of breast cancer." (PMID 28147343, 2017).
clear cell renal cell carcinoma (1 paper, 2025). "For example, RPS20 drives clear cell renal cell carcinoma (ccRCC) progression by co-activating the AKT-mTOR and ERK-MAPK signaling cascades." (PMID 40710323, 2025).
Coronary artery atherosclerosis (1 paper, 2025). "Coronary artery atherosclerosis (LAD-lesion area) was positively correlated with WDR62 and MARS1 transcript levels, and negatively correlated with FGGY, PAQR8, and RPS20 transcript levels (p < 0.05)." (PMID 40709334, 2025).
COVID-19 (1 paper, 2023). A disease caused by infection with severe acute respiratory syndrome coronavirus 2. "Our analysis revealed a downregulation of FXYD, HLA-DRB1, and RPS20 in memory B cells; MTATP8 and HLA-DQA1 in naïve cells; RPS4Y1 in activated B cells; and IGHV3-73 in plasma cells in COVID-19 patients." (PMID 36826040, 2023).
Familial adenomatous polyposis (1 paper, 2022). Familial adenomatous polyposis (FAP) is characterized by the development of hundreds to thousands of adenomas in the rectum and colon during the second decade of life.
gastric cancer (1 paper, 2018). A primary or metastatic malignant neoplasm involving the stomach. "Kaplan-Meier analysis showed that high mRNA expression of GNL1 and RPS20 was strongly associated with decreased overall survival of gastric cancer patients." (PMID 30061673, 2018). "Finally, the inverse correlation of GNL1 and RPS20 expression in primary colon and gastric cancers with patient survival strengthen their critical importance during tumorigenesis." (PMID 30061673, 2018). "Analysis of in vivo expression pattern of GNL1 and RPS20 in colon and gastric cancers from BioXpress database indicates positive co-relation, supporting the notion that GNL1-RPS20 co-operation may be important for cell growth during tumorigenesis." (PMID 30061673, 2018). "In addition, analysis of gene expression databases suggested that the expression of GNL1 and RPS20 in primary colon and gastric cancers inversely correlated with patient survival further strengthen their critical role in tumorigenesis." (PMID 30061673, 2018). "Expression of GNL1 and RPS20 induced the colony forming ability of colon and gastric cancer cell lines provided evidence for the role played by GNL1 and RPS20 during cancer progression." (PMID 30061673, 2018).
intracranial hemorrhage (1 paper, 2025). Bleeding within the SKULL, including hemorrhages in the brain and the three membranes of MENINGES. "Functional studies using the CRISPR/Cas9-mediated knockout of rps20 revealed an impaired growth of central arteries in the hindbrain and a marked increased intracranial hemorrhage incidence." (PMID 40710323, 2025). "Notably, we found ~40% of rps20-KO zebrafish larvae exhibited intracranial hemorrhage compared to the ctrl zebrafish larvae." (PMID 40710323, 2025).
melanoma (1 paper, 2018). A malignant, usually aggressive tumor composed of atypical, neoplastic melanocytes. "Additionally, six cancer cohorts – prostate, breast, liver, lung, melanoma, and head and neck – contained tumor clusters distinguished by overexpression of RPL8, RPL30 and RPS20, with shared expression patterns of 19 other RPTs." (PMID 29530001, 2018).
renal cell carcinoma (1 paper, 2024). "RPS20 has also been demonstrated to facilitate the proliferation and metastasis of renal cell carcinoma cells by stimulating the activity of AKT–mTOR and ERK–MAPK signaling pathways." (PMID 38838053, 2024).
Shwachman-Diamond syndrome (1 paper, 2018). "Gene expression profiles of bone marrow mononuclear cells from patients with Shwachman-Diamond syndrome revealed significant downregulation of RP genes, including RPS9, RPS20, RPL6, RPL15, RPL23, and RPL29, or upregulation of RPS27." (PMID 29954325, 2018).
tumor syndrome (1 paper, 2023). "Other genes such as RPS20 (associated with MMR-proficient, non-polyposis CRC; RPS20-associated hereditary CRC) and NTHL1 (associated with polyposis hereditary CRC; NTHL1-tumor syndrome) are less prevalent and may be added to CRC NGS panels." (PMID 37965459, 2023).
cancer (17 papers, 2006 to 2023). A tumor composed of atypical neoplastic, often pleomorphic cells that invade other tissues. "In family 92, a large Amsterdam I positive family with 13 cases of CRC (IHC analysis in two tumors from two different patients showed normal expression of the MMR-proteins) in addition to other cancers, we identified the RPS20 variant c.98A>T, p.(Glu33Val)." (PMID 33193653, 2020). "Thus, it is not surprising that, as mentioned in the Introduction, mutations in the RPS20 gene, which correspond to the disruptive mutations in the uS10 ribosomal protein described in the current study, can increase the risk of developing cancer." (PMID 35682850, 2022). "According to these criteria, five genes (RPL5, RPL11, RPS5 (uS7), RPS20 (uS10), RPSA (uS2)) were significantly mutated in four different cancer types." (PMID 28147343, 2017). "Similar to RPS20, as analyzed above, all of the homologues of RPS20 can also be functional components of exosomes, implying the differentiated role of RPS20 and its homologues for the detection of cancer by liquid biopsy." (PMID 29152097, 2017). "Genes encoding components of the translation machinery, the mitochondrial ribosomal protein MRPL15 and cytosolic ribosomal proteins RPL7 and RPS20, are located in this region, highlighting the need for enhanced translation in cancer cells." (PMID 16982006, 2006). "A recent study identified six ribosomal protein genes as potential cancer drivers in five different cancer types: uL18/RPL5, uL5/RPL11, uL23/RPL23A, uS7/RPS5, uS10/RPS20, and uS2/RPSA82." (PMID 29674660, 2018). "We screened mutation and copy number data of respectively 4926 and 7322 samples from 16 cancer types and identified six altered genes (RPL5, RPL11, RPL23A, RPS5, RPS20 and RPSA)." (PMID 28147343, 2017).
infection (8 papers, 2018 to 2023). The state of being infected such as from the introduction of a foreign agent such as serum, vaccine, antigenic substance or organism. "On day 8 after infection, the expression levels of RPS11 and RPS20 were upregulated to varying degrees." (PMID 35313969, 2022). "We found that ribosomal proteins, such as ribosomal protein S20 (RPS20), S14 (RPS14), L15 (RPL15), and S14 precursors, which are generally expressed in bradyzoites, were highly expressed in the ME49 strain 72 h post-infection, indicating bradyzoite formation in the brain organoids." (PMID 32820712, 2020).
tumor (7 papers, 2015 to 2025). "When overexpressed, RPS11 and RPS20 were generally diffusely upregulated in the tumor cell population." (PMID 26506620, 2015). "Importantly, some RP genes (e.g., RPL5, RPL11 and RPS20) are known to be tumor-suppressor genes, which is not the case for GATA1." (PMID 35328001, 2022).
RPS20 also shares sentences with these, for which no sentence is quoted: endometrial cancer (2 papers); glioma (2); pancreatic cancer (2); prostate carcinoma (2); acute myeloid leukemia (1); cerebellar ataxia (1); chronic lymphocytic leukemia (1); HCMV infection (1); hepatoma (1); lymphoma (1); Lynch syndrome (1); malignant brain tumor (1); mutyh-associated polyposis (1); myelodysplastic syndrome (1); Pancytopenia (1); Peutz-Jeghers syndrome (1); polyposis (1); psoriasis (1); scrapie (1); Sepsis (1); T-cell acute lymphoblastic leukemia (1); type 2 diabetes (1).